FOXO1 (forkhead box O1)
Diseases named in the same sentence as FOXO1 in open-access papers (continued):
Sharing a sentence is not in itself a finding about the gene and the disease.
diabetes (continued). "Besides, enhanced autophagy and FoxO1 protein expression by diabetes were dose-dependently suppressed by Ang IV treatment." (PMID 34522203, 2021). "Modulation of the AKT/FOXO1 signaling pathway might alter redox balance that contributes to delayed wound healing in diabetes." (PMID 33505585, 2021). "We showed that elevation of FoxO1 was a crucial factor associated with the increase of pro‐inflammatory factors, MMP expression and SMCs phenotype switching, resulting in the development of pathological vascular remodelling in type 1 diabetes mellitus (T1DM)." (PMID 33108705, 2020). "Based on in vivo observation, we postulated that FoxO1 may have contributed to vascular remodelling in diabetes via its impact on cellular phenotypic switching." (PMID 33108705, 2020). "We wondered whether FoxO1 mediated vascular remodelling in diabetes was attributable to the enhancement of apoptosis under hyperglycaemic environment." (PMID 33108705, 2020). "FoxO1 overexpression in liver and pancreatic β‐cells is sufficient to induce diabetes in mice." (PMID 33108705, 2020). "Furthermore, there are sex-dependent changes in the expression of hepatic gluconeogenic genes including the transcription factor forkhead box o1 (Foxo1) in the offspring exposed to maternal high-fat diet, diabetes or alcohol." (PMID 32494846, 2020). "Given the critical role of FOXO family in ROS homeostasis in diabetes mellitus, we hypothesized that FOXO1 would be effective in inhibiting HG-induced ROS production." (PMID 30962862, 2019). "To determine the role of FOXO1 in this damage and the underlying mechanisms, we established a tissue-specific transgenic (Tg) diabetic mouse model overexpressing Foxo1 and determined the effects on physiological parameters, extent of apoptosis and interstitial fibrosis, and production of ROS." (PMID 30962862, 2019). "In early phases of diabetes, FOXO1 is dephosphorylated and translocates into the nucleus." (PMID 31156786, 2019). "Interestingly, some ATAC-seq peaks overlapping with both these marks are annotated to genes that have islet specific function and/or have been associated with diabetes by GWAS e.g., TCF7L2, SLC2A2, FOXO1 and HNF1B27." (PMID 31123324, 2019). "Thus, it is still unclear how maternal diabetes leads to the decreased phosphorylation of Foxo1 in the liver of STZ male offspring." (PMID 31308441, 2019). "Consequently, we confirmed reduced activity of mTOR signaling components and higher expression of atrophy-related markers typified by FoxO1/atrogin-1/MuRF1 and myostatin-Smad2/3 signaling during the course of diabetes." (PMID 30510624, 2018). "The results indicate that the impact of diabetes on MMP9 is FOXO1 dependent." (PMID 28874756, 2017). "In summary, FOXO1 regulation may contribute to the detrimental outcomes of the cardiac cells in diabetes, accelerating the development of DCM, one of the predominant cardiac difficulties in diabetic patients." (PMID 26956801, 2016). "Studies have shown that cardiac FoxO1 is increased in diabetes." (PMID 26783539, 2016). "Moreover, the Akt substrate Forkhead box protein O1 (FoxO1) is involved in the regulation of proliferation and apoptosis, so the insulin signaling network has a major role not only in obesity and diabetes but also in cancer." (PMID 27149630, 2016). "Therefore, it appears that diabetes alters the function of FOXO1 so that it switches from being a pro-healing anti-apoptotic transcription factor to one that fails to up-regulate TGF-β1 and becomes pro-inflammatory and pro-apoptotic." (PMID 25226535, 2014). "Therefore, it is in high possibility that serious downexpression of miR-182 increases expression of FOXO1 which contributes to hyperglycemia in diabetes." (PMID 25530976, 2014). "IGF-I treatment was effective in increasing FOXO1, thereby suggesting that it could be considered as a potential treatment in CF patients possibly to prevent and treat cystic fibrosis-related diabetes." (PMID 25299696, 2014).
diabetes (continued). "Since LTKO mice had lower glucose levels relative to wild-type mice on regular chow diet, we went on to test whether deletion of hepatic FoxO1/3/4 might protect mice from developing high-fat diet-induced diabetes." (PMID 24015318, 2013). "We propose that dysregulation of FoxO1 activity in the pancreas could account for the development of diabetes and pancreatic cysts." (PMID 22384192, 2012). "Moreover, diabetes-enhanced TNF-α activates FOXO1 in chondrocytes in vivo by enhancing its nuclear localization." (PMID 22454632, 2012). "We propose that dysregulation of FoxO1 activity in the pancreas may account for the development of diabetes and pancreatic cysts." (PMID 22384192, 2012). "Interestingly, high levels of FOXO1 have been reported in diabetes, but the scope of these studies has focused on the effect of FOXO1 on mRNA levels of genes that increase glucose production, thereby contributing to hyperglycemia in diabetes." (PMID 20300563, 2010). "Since diabetes can increase FOXO1 activity and potentiate cells toward apoptosis, it is logical to assume that FOXO1 may also play a role in apoptosis of pericytes." (PMID 20300563, 2010). "Interestingly, FOXO1 in diabetes is mostly known for its effect on insulin regulation of glucose production and insulin sensitivity." (PMID 20300563, 2010). "Since DCs are a rapid-onset and frequent complication of diabetes mellitus, the authors attempted to define whether β-CM-7 could exert antioxidant protection through the modulation of transcription factors such as FoxO1 and Sp1, known regulators of oxidative stress responses." (PMID 40507153, 2025). "Thus, activation of the FoxO1-zDHHC4-CD36 axis drives metabolic dysfunction in diabetes." (PMID 40357580, 2025). "Taken together, FoxO1 dysregulations could exacerbate damages in myocardial cellular processes, accelerating the development of diastolic dysfunction during DbCM, a major complication in people with diabetes." (PMID 39206323, 2024). "Thus, the enhancement of FoxO1 activity contributes to dysregulated apoptosis and autophagy in diabetes, and targeting these perturbations could alleviate the progression of DbCM." (PMID 39206323, 2024). "Furthermore, FOXO1 ́s negative regulatory influence on skeletal muscle mass and type I fibre gene expression has been proposed, potentially contributing to sarcopenia, obesity, and diabetes in humans." (PMID 39283487, 2024). "Thus, we currently lack enough information on whether FoxO1 or its pathways could be a therapeutic target during DbCM in people with diabetes." (PMID 39206323, 2024). "Thus, FOXO1 is an indispensable factor in diabetes research." (PMID 36964488, 2023). "To evaluate the translational value of this triple combination therapy in an autoimmune model of diabetes, we used Repsox and the γ-secretase inhibitor PF-03084014, currently in phase II trials for the treatment of different forms of cancer, in combination with the chemical FOXO1 inhibitor FBT10." (PMID 36282594, 2022). "Findings of our in vitro studies provide a clue that activation of FoxO1 and/or FoxO3a may prove to be an effective approach in combating myocardial ischemia reperfusion injury in diabetes, despite that further studies in in vivo models of myocardial I/R is merited." (PMID 34753510, 2021). "Interestingly, ND αCD4 only delayed the development of overt diabetes in BDC.Foxo1–/– mice." (PMID 34314385, 2021). "Interestingly, most transcripts namely, Pck2, Prkab2, Pik3r1, Foxo1, Irs1 and Pik3r5 are commonly involved in these pathways and this suggests a significant involvement and contribution of these genes in aberrant skeletal muscle metabolism during diabetes." (PMID 34190986, 2021). "Therefore, down-regulation of FOXO1 in T2DM may be a new strategy for the treatment of diabetes mellitus." (PMID 31156786, 2019).
diabetes (continued). "To investigate whether or not cellular translocation of FoxO1 is critically influenced by our diabetes‐associated HDAC4 mutations, we transfected wild‐type and three mutated HDAC4s (p.H227R, p.D234N, p.E374K) into mouse MIN6 β‐cells and examined FoxO1 with immunostaining." (PMID 30968599, 2019). "Although the relevance of our data to the clinical setting requires further investigation, they provide compelling evidence for the identification of HMGA1 as a novel nuclear activator of FoxO1 gene transcription, which may help explaining noted differences in diabetes phenotypes." (PMID 29052178, 2018). "The discrepancy between the in vivo and in vitro models in relation to the effect of FOXO1 on PP2A could be the presence of excess lipids brought in by the FOXO1–CD36 pathway observed with diabetes, which turns on PP2A, thereby activating BAD stimulated apoptotic process." (PMID 26956801, 2016). "Furthermore, FOXO1 is thought to play a key role in the development of type 2 diabetes mellitus." (PMID 25299696, 2014). "In endothelial cells and pericytes increased FOXO1 activation by inflammatory mediators or advanced glycation end products, both of which are elevated in diabetes, leads to greater cell death and may be an important component of some microvascular complications such as diabetic retinopathy." (PMID 25226535, 2014). "Under insulin resistance conditions, FoxO1 becomes less phosphorylated at the inhibitory serine/threonine residues and therefore more active to promote expression of these gluconeogenic genes, which may contribute to hyperglycemia in diabetes." (PMID 24015318, 2013). "Interestingly, it was observed that O-β-GlcNAc on hepatic FoxO1 increased in diabetes." (PMID 22489133, 2012). "In a model of diabetic heart injury, for instance, vitamin D reportedly attenuated diabetes-related cardiac damage and autophagy through VDR-mediated signaling and the consequent inhibition of FoxO1 translocation to the nucleus." (PMID 40564179, 2025). "Genetic knockout of AMPK or FOXO1 abrogated the protective effects of rFGF4 against diabetes-induced renal injury, underscoring the critical role of the AMPK-FOXO1 axis in mediating the therapeutic effects of FGF4 in DKD." (PMID 41290710, 2025). "Further animal experiments confirmed that compared with Vehicle-treated diabetic cognitive impairment mice, AVE 0991-treated diabetic cognitive impairment mice exhibited reduced p-AKT protein levels, and increased protein levels of FOXO1 and PACAP." (PMID 40303297, 2025). "Another study uncovered that iMSC-EVs transferred miR-21-5p and miR-486-5p to promote hippocampal neural stem cells (H-NSCs) proliferation and neurogenesis through inhibiting EphA4, CDKN2C, and FoxO1 expression in diabetes mellitus-postoperative cognitive dysfunction (DM-POCD)." (PMID 39135947, 2024). "Our findings reveal that during diabetes, IR, PI3K, AKT, AMPK, and FOXO-1 gene expression in the brain are dramatically downregulated, but PPAR-γ gene expression is significantly increased, leading to hyperglycemic condition in diabetic rat." (PMID 38683825, 2024). "As for diabetes; it also increased the expression of iNOS, NF-κB, and PPAR-γ but decreased that of FOXO-1 in the cortical tissue, supporting the importance of the inflammatory process in neuronal death." (PMID 38683825, 2024). "We examined the effect of CdCl2 exposure on FOXO1 expression due to the involvement of the FOXO proteins and sirtuin 1 (SIRT1) in glucose handling, development of diabetes, and potential role in the development of PDAC." (PMID 34905088, 2022). "Subjects with diabetes often exhibit hyperinsulinemia, glucagon dysregulation, hyperglycemia-induced microinflammation, oxidative stress, endoplasmic reticulum (ER) stress, and/or dyslipidemia, which might regulate the SerpinB1 expression via hepatic regulation of FoxO1." (PMID 36331940, 2022).
diabetes (continued). "However, a recent study suggests that inadequate autophagy with impaired autophagosome-lysosomal fusion exists in the aortic intima and endothelial cells from diabetic patients and that FoxO1 may inhibit autophagosome-lysosome fusion and lead to endothelial autophagic-apoptosis in diabetes." (PMID 36035917, 2022). "Treatment of BDC mice with αCD3 Ab (clone 2C11), a therapy shown to reverse diabetes in NOD mice, however, decreased expression of Foxo1-axis genes but increased expression of TCR-driven genes (Irf4, Nr4a1, Cd25, Cd69, Tbx21) in PLN BDC CD4+ T cells." (PMID 34314385, 2021). "Liraglutide inhibited the phosphorylation of FoxO1 and increased Mn-SOD expression in the diabetic kidneys." (PMID 33859563, 2021). "Because of the direct action of ERK3/MK5 complex on the FOXO1-mediated transcriptional signaling, we decided to test the impact of ERK3 on the development of obesity and diabetes in vivo." (PMID 32139423, 2020). "In conclusion, we observed that SET8 expression was decreased, FOXO1 and PTEN expression was increased, and endothelial inflammation was augmented in people with diabetes and diabetic rats." (PMID 33028948, 2020). "Therefore, the present study aims at elucidating how RPTCs respond to diabetes-induced ROS accumulation under the condition of FOXO1 overexpression, contributing to interstitial fibrosis and apoptosis, and at determining whether the effects occur downstream of the TXNIP-TRX." (PMID 30962862, 2019). "It should further be noticed that genes of importance for islet function and diabetes such as PDX1, TCF7L2, FOXA2, FOXO1, NEUROD1 and BACH2 have C1, C3 or both these sites at their ATAC-seq open chromatin regions." (PMID 31123324, 2019). "In the present study, we studied the expression of Foxo1, Gsk3β and PI3K-Akt-mTOR in the brain of streptozotocin-induced type 2 diabetes mellitus Wistar rats." (PMID 30041644, 2018). "Gene expression of other insulin-responsive metabolic enzymes, including transcription factors Forkhead Box O1 and O6 (FoxO1, 6) and the fatty acid transporter, CD36, and fatty acid synthase were both modulated by diabetes but were unaffected by SRT3025." (PMID 30228292, 2018). "In diabetes, the activation of myocardial STAT3 was markedly decreased, whereas the expression of FoxO1 was upregulated." (PMID 26783539, 2016). "The high expressions of FoxO1 and CD36 in diabetic groups displayed an aggravating cardiac injury and suggested the correlation between FoxO1, CD36, and lipid metabolism disorder in diabetes." (PMID 26783539, 2016). "In conclustion, GB extract feeding inhibits the decrease of expression of FOXO1 and PPARγ, and increases insulin signaling, contributing to the improvement of insulin sensitivity in aged mice.Therefore, GB extract might have a potential to ameliorate age-related metabolic disorder such as diabetes." (PMID 25912041, 2015). "In stratified analysis according to gender, the history of smoking, hypertension, diabetes mellitus, hyperlipidemia and the metabolic syndrome, we further explored that neither the variants of FoxO1 nor the variants of FoxO3 might be associated with CHD (p>0.05)." (PMID 24489705, 2014). "Haploinsufficiency for FoxO1 resulted in an increase of β cells and rescued both IRS-2 knockout mice and Pdk-1 knockout mice from diabetes via restoration of Pdx1 expression in β cells." (PMID 22384192, 2012). "Furthermore, inhibiting DYRK1B kinase activity using AZ191 affects FOXO1 stabilization on chromatin, improving hyperglycemia in diabetic mice, highlighting the therapeutic potential of AZ191 in diabetes treatment." (PMID 40287828, 2025). "Studies have found that in vivo lentivirus-mediated overexpression of FoxO1 inhibited EMT in podocytes of diabetic mice by suppressing TGF-β1/Smad3/ILK, significantly alleviating diabetes-induced renal injury and proteinuria, consistent with in vitro cell experimental results." (PMID 39382800, 2024).
diabetes (continued). "Remarkably, the administration of LPE-polyflavonoids upregulated the expression of the pancreatic and hepatic PI3K, AMPK, and FOXO1 genes, emphasizing the efficiency of the LPE in orchestrating all the signaling pathways necessitated to reduce the diabetes mellitus." (PMID 37765275, 2023). "Collectively, these findings emphasize the pivotal functions of flavonoids, including LPE-polyflavonoids, as countermeasures to oxidative stress and other complications derived from diabetes by orchestrating the expressions and functions of PI3K, p-AKT, and FOXO1." (PMID 37765275, 2023). "We also found that Foxo1 transcriptionally suppresses cilia gene expression and impairs cilia formation and deletion of Foxo1 rescues the negative impact of diabetes on the fracture repair process." (PMID 37591875, 2023). "Expression of FOXO1 in pancreatic tissue in a diabetic state was significantly reduced compared to patients/mice without diabetes." (PMID 34935260, 2022). "A recent study evaluated the expression levels of FOXO1 gene in 138 non-ST elevated MI (NSTEMI) patients with and without type 2 diabetes, which revealed that FOXO1 was elevated in NSTEMI patients irrespective of the presence of diabetes." (PMID 36407428, 2022). "Despite the rapid development of overt diabetes, the number of splenic, PLN, and pancreas-infiltrating CD4+ T cells was reduced in BDC.Foxo1–/– mice approximately 10-fold compared with BDC.Foxo1+/+ mice, which is consistent with reduced peripheral T cell numbers in Foxo1-deficent mice." (PMID 34314385, 2021). "Furthermore, the expression of FOXO1, GS, GLUT2, and PFK-1 in the treatment group was elevated compared to the diabetes group." (PMID 34960064, 2021). "Based on the majority of the available evidence, dysregulation of FoxO1 activity may reduce the antioxidant effect to respond to OS, leading to apoptosis, inflammation, and ECM accumulation in diabetic kidneys." (PMID 33859563, 2021). "The positive effect of MNAM on insulin sensitivity in diabetes was abrogated, suggesting that the SIRT1/FOXO1 signal pathway could regulate the effects of MNAM in obese T2DM model." (PMID 32280711, 2020). "Our data clearly confirmed the beneficial effects of DKE on PPARγ activation and FOXO1 deactivation in both the in vivo and the ex-vivo models and thus, scientifically approved the validity of the traditional use of DKE against diabetes and some of its complications." (PMID 30376839, 2018). "A recent study disclosed that FOXO1 supports inflammation during diabetes by increasing the expression of TLR4, recommending that FOXO1 may function as an essential regulator of inflammatory reactions during obesity and diabetes mellitus." (PMID 26956801, 2016). "In diabetes, both intrinsic (mitochondrial cytochrome c mediated) and extrinsic (death receptors like Fas or TNF α mediated) apoptosis are reported to be augmented and FOXO1 is suggested to increase the expression of caspases and cell death receptors." (PMID 26956801, 2016). "In the case of FoxO-1, neither diabetes nor the treatment with tungstate modified the expression of this factor." (PMID 22905122, 2012). "Recent studies show that FOXO1 promotes inflammation during diabetes by enhancing TLR4-mediated signaling, suggesting FOXO1 as a key mediator of inflammatory responses during obesity and diabetes." (PMID 22454632, 2012). "Diabetes increased chondrocyte apoptosis through a mechanism that involved enhanced production of TNF-α, which stimulates chondrocyte apoptosis and upregulates mRNA levels of apoptotic genes through FOXO1 activation." (PMID 20200974, 2010). "Moreover, human islets from donors with and without diabetes treated with osteocalcin showed a reduced nuclear FOXO1 and an increase in nuclear PDX1." (PMID 40585255, 2025).